HDAC1 (histone deacetylase 1)
Diseases named in the same sentence as HDAC1 in open-access papers (continued):
Sharing a sentence is not in itself a finding about the gene and the disease.
cancer (continued). "HDAC1 is essential for cancer development: high expression of HDAC1 predicts poor prognosis in multiple cancer types, such as lung, breast, ovarian, prostate, and renal cancer." (PMID 33482915, 2021). "Mechanistically, tambulin downregulates HDAC1, which in turn regulates the Bcl-2/caspase signaling pathway and promotes cancer cell apoptosis." (PMID 32903420, 2020). "Several of these new derivatives not only showed excellent HDAC1 inhibitory effects, but also displayed significant growth inhibitory activities against four human cancer cell lines." (PMID 32046013, 2020). "Most compounds showed excellent HDAC1 inhibitory activities and also displayed significant growth inhibition against different human cancer cells." (PMID 32046013, 2020). "To check if BRG1 creates a multi-enzyme complex with EP300 and HDAC1 in proliferating cancer cells, we searched for the latter two enzymes in BRG1 co-immunoprecipitates." (PMID 32033115, 2020). "Overexpression of DNA methyltransferases (DNMTs) and histone deacetylase 1 (HDAC1) have been reported in several cancers." (PMID 32337014, 2020). "Extensive genes have been identified as the target of miR-761 in numerous cancers, including HDAC1, Rab3D, Runx3, Mitofusin-2, CXCR1, TRIM29, MSI1, ING4, TIMP2, and GSK3β." (PMID 32185226, 2020). "In support of a nuclear control of autophagy, inhibition of HDAC1 has been shown to induce autophagy and to promote cell death in several types of cancer cells." (PMID 31399583, 2019). "EZH2, LSD1, DNMT1, and HDAC1 are co-expressed in many types of cancer cells, as well as in neural progenitor/stem cells." (PMID 31130994, 2019). "Taken together, our studies reveal a new, evolutionarily conserved mechanism of H3K79me regulation by Rpd3/HDAC1 with relevance for cancer development." (PMID 31304633, 2019). "Using class-specific inhibitors and selected siRNAs, we demonstrated that HDAC class I and in particular HDAC1 is largely responsible for this effect across different types of cancer." (PMID 31395086, 2019). "As specific HDAC inhibitors are developed for use in cancer and in various immune and neurological diseases, analysis of their impact on global and specific effects of HDAC1 and HDAC2 should be considered." (PMID 30926862, 2019). "Reports have indicated that maspin serves as an endogenous inhibitor of HDAC1 activity, which leads to the induction of apoptosis in several cancer cells." (PMID 31861435, 2019). "In this study, we showed that Class I HDACs and in particular HDAC1 are required for RUNX2 efficient transcription in cancer." (PMID 31395086, 2019). "It is found that increasing oxidative stress by H2O2 upregulated histone deacetylase 1 (HDAC1) in cancer cell lines." (PMID 30881600, 2019). "The N-hydroxycinnamamide-based HDAC inhibitor with HDAC1/3 dual selectivity has shown promise as an anti-cancer drug." (PMID 30583572, 2018). "Since HDAC inhibitors are already used in cancer therapy and are on trials for other non tumoral/fibrotic diseases, the understanding of the role of HDAC1 in the maintenance of a mesenchymal state in MCs has both a basic and a translational relevance." (PMID 29855565, 2018). "And HDAC1 inhibitors are widely tested as single or combined agents in clinical trials for multiple types of cancer, including GBM35,36." (PMID 30302016, 2018).
cancer (continued). "Previous studies consider HDAC1, –3 and –7 as tumour biomarkers and knockdown of HDAC1, –2, –3 and –6 in a variety of cancer cell lines can promote apoptosis and cell cycle arrest while HDAC1, –2 and -4 are required to maintain cancer cell survival in vivo." (PMID 29899862, 2018). "(B) After quantification and normalization, the expression change of HDAC1–3 and B7-H1 between each pair of cancer and adjacent tissue was presented." (PMID 30537988, 2018). "In the present study, we present evidence that the inhibition of HDAC1 enhances the anti-cancer effects of statins." (PMID 28481295, 2017). "According to the analysis, HDAC1 was considered as the most potential hub gene for Cancer versus Normalcy group." (PMID 29312619, 2017). "Inhibiting HDAC1 enhanced the anti-cancer effects of statins through downregulation of GGTase-Iβ expression, and thus further inactivation of RhoA." (PMID 28481295, 2017). "The enhancement by inhibiting HDAC1 of statin-induced anti-cancer effects was also confirmed in nude mice with xenografts." (PMID 28481295, 2017). "Downregulation of HDAC1 induces cell cycle arrest, decreases viability, and increases apoptosis in cancer cells and fibroblasts." (PMID 28624794, 2017). "The best characterised and probably biologically most relevant HDAC in human cancers are class I isoforms HDAC1, HDAC2, and HDAC3." (PMID 28785170, 2017). "In the current study, only mevastatin and atorvastatin were used with a pan-HDAC inhibitor or the HDAC1 inhibitor to examine anti-cancer effects in two cell lines." (PMID 28481295, 2017). "RhoA was determined as the key target for the enhancement of statin-induced anti-cancer effects by HDAC1 inhibitor." (PMID 28481295, 2017). "Inhibiting HDAC1 blocked the statin-induced upregulation of geranylgeranyl transferase type Iβ subunit (GGTase-Iβ), resulting in an enhancement of the anti-cancer effects of statin." (PMID 28481295, 2017). "Together, these results demonstrate that selective pharmacological inhibition of HDAC1/2 is sufficient to mediate synergistic anti-cancer activity in combination with azacitidine in preclinical models of AML." (PMID 28060870, 2017). "Our results suggested that the combination of HDAC1 inhibitor and a statin would be a potential new regimen for cancer therapeutics." (PMID 28481295, 2017). "For example, HDAC1 has been demonstrated to be overexpressed in many cancers, such as in breast, lung and renal cell cancer, as well as in classical Hodgkin's lymphoma." (PMID 28424407, 2017). "The combination of HDAC1 inhibitor and statin would be a potential new regimen for cancer therapeutics." (PMID 28481295, 2017). "Studies show WA to regulate mechanisms involved in the apoptotic pathway and our findings provide a framework to begin establishing epigenetic linkage of the combined WA and SFN with HDAC1 and cell cycle progression in cancer." (PMID 28534825, 2017). "The enhancement by inhibiting HDAC1 of anti-cancer effects of statins was similar to that of pan-HDAC inhibitor SAHA." (PMID 28481295, 2017). "An overwhelming number of studies have proven that Histone Deacetylase 1 (HDAC1) is tightly correlated with cancer." (PMID 28424407, 2017). "It has been reported that HDAC1 is critical for mitosis in cancer cells and its absence induces activation of caspases leading to apoptosis mediated cell death." (PMID 27655674, 2017). "A combination of statin with HDAC1 or GGTase-I inhibitor would be a new strategy for cancer chemotherapy." (PMID 28481295, 2017). "Recent study also demonstrated that HDAC1-induced decreased expression of thioredoxin binding protein-2 will result in decreased sensitivity of cancer cells to oxidative stress induced cytotoxicity." (PMID 27655674, 2017). "Our results support that Daxx can act as a repressor in controlling HIF-1α/HDAC1/Slug-mediated cancer cell invasion and is a potential therapeutic target for inhibition of cancer metastasis." (PMID 28004751, 2016).
cancer (continued). "In this study, we show that Daxx is a negative regulator of hypoxia-induced EMT and cancer metastasis that acts by inhibiting the HIF-1α/HDAC1/Slug pathway." (PMID 28004751, 2016). "For example, histone deacetylase 1 gene (HDAC1) has been reported as a TSG during the cancer initiation, but as an oncogene during the tumor maintenance process." (PMID 26590405, 2016). "Because APE1 is known to be phosphorylated, it is possible that such modification of APE1 in cancer cells enhances its interaction with p300 to induce acetylation or decrease its interaction with HDAC1/SIRT1 to maintain enhanced level of APE1 acetylation." (PMID 27655688, 2016). "Statistical analysis revealed that HDAC1 level significantly increased in cancer tissues and it promotes the invasion of GBC cells in vivo and in vitro." (PMID 27092878, 2016). "Pathway results showed that seed genes PTGS2, HDAC1, JUN, and SLC2A1 were enriched in pathway in cancer, seed genes HDAC1 and CDC20 were involved in cell cycle, and seed gene MTHFR participated in methane metabolism." (PMID 27034707, 2016). "Specifically, we showed that Daxx suppresses cancer metastasis by interfering with Slug E-box binding and competing for recruitment of the effector HDAC1 by directly binding to the Slug DNA-binding domain." (PMID 28004751, 2016). "The reduction in the expression of HDAC1 by AN-7 was already demonstrated in other cancer cell lines as well." (PMID 26752418, 2016). "The role of individual histone deacetylases (HDACs) in the regulation of cancer cell proliferation was investigated using siRNA-mediated knockdown (HDAC1, HDAC2, HDAC3, HDAC4 and HDAC7) in HeLa cells." (PMID 26560874, 2016). "Genetic and pharmacological inhibition studies identified HDAC1 as a key determinant in the reversal of carcinoma immune escape." (PMID 26862729, 2016). "Previously, miR-449a had been identified in various types of cancer tissues where it plays a tumor-suppressive role, in part through targeting HDAC1 and activating p27 expression." (PMID 25886011, 2015). "We find that para-substituted hydroxamic acid analogs of 9b inhibit HDAC activity showing preference for HDAC6 over HDAC1 and have cancer selective antiproliferative properties." (PMID 26698121, 2015). "Currently, inhibiting DNA repair mechanisms using a HDAC1,2-selective inhibitor as a therapeutic strategy for other cancers is under investigation." (PMID 25605023, 2015). "Numerous reports indicate HDACs are overexpressed in many cancers, especially HDAC1, HDAC2, and HDAC8 are overexpressed in colon cancer, and inhibit specific tumor suppressor genes, resulting in an aberrant epigenetic status compared to adjacent normal cells." (PMID 25015091, 2014). "in vitro fluorometric HDAC activity assay showed that MPT0G030 effectively inhibited Class I HDACs (HDAC1~3), which were overexpressed in many malignant neoplasms." (PMID 25015091, 2014). "In this study, we report that a conservative substitution of maspin D346 by glutamic acid (E) resulted in its dominant nuclear distribution and increased interaction with HDAC1 in multiple cancer cell lines." (PMID 24278104, 2013). "The present results suggest that wogonin has multiple anti-cancer effects associated with degradation of c-Myc, SKP2, HDAC1 and HDAC2." (PMID 24265759, 2013). "In general, histone acetylation enables genes to be expressed, and HDAC1/2 activity is required to repress epithelial markers during cancer cell invasion and metastasis." (PMID 23741434, 2013). "Our laboratory also discovered that endogenous maspin binds to and inhibits the activity of histone deacetylase 1 (HDAC1), which is a major nuclear deacetylase of class I that is up-regulated in many types of cancers." (PMID 24278104, 2013). "The level of HDAC1 associated with the control promoter GAPDH was unchanged between cell lines, but was more than doubled at RGS10-1 promoters in the cancer cell line, compared to IOSE cells." (PMID 23533674, 2013).
cancer (continued). "HCC patients with high expression of HDAC1 showed higher incidence of cancer cell invasion into the portal vein, poorer histological differentiation, more advanced tumor-node-metastasis (TNM) stage and low survival rate." (PMID 22496786, 2012). "It was also found that highly expression of HDAC1 in cancer cells is correlated with chemotherapy resistance and poor prognosis in a series of carcinomas." (PMID 22496786, 2012). "In cancer cells, HDAC1 represses the expression of tumor suppress genes such as p21/WAF1/CIP1 and Bax, leading to aberrant cell proliferation and cell viability." (PMID 22496748, 2012). "Previous studies have shown that HDAC1 was overexpressed in many cancers, including gastric, colorectal and pancreatic carcinomas." (PMID 22455563, 2012). "Here, we describe for the first time in a human cancer cell line, a transcriptional comparison of treatment by two structurally unrelated HDACi; belinostat and valproic acid with the KD of HDAC1, 2 and 3 isoforms." (PMID 18789133, 2008). "The reduced viability that we observe upon individual HDAC1, -2 and -3 knockdown has been published on class I HDAC KD in cancer cells, especially via proliferation for HDAC1 and -3, and via apoptosis for HDAC2." (PMID 18789133, 2008). "Experimental evidence suggests that both HDAC1 and Rpd3 deacetylases play significant roles in aging and cancer." (PMID 17578512, 2007). "Class I HDAC activity is key for uncontrolled proliferation of cancer cells, since downregulation of HDAC1 and HDAC3 expression results in increased histone acetylation and inhibition of HeLa cell proliferation." (PMID 18000499, 2007). "We also screened HDAC1, HDAC2, SUV39H1, and SUV39H2 for mutations in 65 cancer cell lines and 116 primary tumours." (PMID 16638127, 2006). "Mutation analysis of HDAC1, HDAC2, SUV39H1, and SUV39H2 revealed only two out of 181 cancer samples (both cell lines) with significant coding-sequence alterations." (PMID 16638127, 2006). "In this regard, cancer cells are similar to stem cells, where HDAC1 is required for full cellular growth potential." (PMID 16250917, 2005). "Further, in-vitro scratch assays were performed on U87 MG cells to understand the effect of NEP silencing, as well as its upregulation using certain HDAC1 inhibitors identified through in-silico studies (melphalan, tasimelteon and panobinostat), to study the cancer progression." (PMID 40581884, 2025). "We found that UM171, a clinical phase 2 drug for haematopoietic stem cell transplantation, structurally mimics the cancer-mutated loop and acts as a molecular glue for wild-type KBTBD4 and HDAC1/2, resolving the long-standing puzzle of UM171’s mechanism of action." (PMID 40175372, 2025). "Additionally, the in-vitro scratch assay demonstrated that silencing of NEP augmented cell proliferation, whereas the upregulation of NEP using the HDAC1 inhibitors resulted in decreased cancer proliferation." (PMID 40581884, 2025). "Suppressed the expression of the HDAC1/2 proteins only in the cancer cells." (PMID 39801754, 2025). "HDACs (HDAC1, 2, 3 and 6) overexpression has been confirmed earlier in different cancers." (PMID 40159638, 2025). "Also, MUC1-overexpressed cancer cell lines are preferentially killed by a DNA-PK inhibitor and HDAC1/2 inhibitors." (PMID 38927743, 2024). "Additionally, within the HDAC family, HDAC1 predominantly assumes a pro-cancer function, whereas HDAC6 potentially serves as an anticancer factor." (PMID 38490978, 2024).
cancer (continued). "Our findings reveal a relationship between elevated HDAC1 expression and poor prognoses across multiple cancer types, suggesting that HDAC1 could serve as both a prognostic marker and a therapeutic target." (PMID 39723246, 2024). "After the study of induced pluripotent stem cells (iPS), which enabled dedifferentiation by regulating four genes, an extended study revealed that two regulators, BCL11A and HDAC1/2, have been identified in the gene regulatory network for reprogramming cancer cells." (PMID 38536842, 2024). "Also, TQ has demonstrated a cytotoxic effect in vitro on leukemic cells by inhibiting DNMT1 and HDAC1, representing a potential epigenetic treatment against cancer." (PMID 39769174, 2024). "Moreover, HDAC1’s role in maintaining the self-renewal potential of GBM cancer stem cells complicates treatment efforts, as these cells exhibit resistance to standard therapies." (PMID 39723246, 2024). "Our results suggest that HDAC1 may be used as a prognostic marker for cancer treatment in future clinical practice." (PMID 36644230, 2023). "However, nowadays, the understanding of their role in the pathogenesis of cancer is at fairly early stages compared to the understanding of HDAC1." (PMID 37834214, 2023). "Recent studies have shown that HDAC1 is involved in the pathogenesis of many cancers." (PMID 36644230, 2023). "The HO-AAVPA is a HDAC1 inhibitor and antiproliferative in cancer cell lines." (PMID 36854957, 2023). "HDAC1 increases during immune-editing and contributes to immune refractory cancers, including CESC." (PMID 36900213, 2023). "Importantly, we find that SnoN acts in a sumoylation-dependent fashion to stimulate and inhibit, respectively, the effects of HDAC1 and p300 on EMT-associated morphological and functional changes in breast epithelial and carcinoma cells." (PMID 37414747, 2023). "In gain and loss of function studies, HDAC1 suppresses, whereas p300 promotes, TGFβ-induced morphogenetic changes associated with EMT-related events in three-dimensional multicellular organoids derived from mammary epithelial cells or carcinomas." (PMID 37414747, 2023). "The expression of HDAC1 in this study was low in most carcinomas." (PMID 38028583, 2023). "Collectively, our study reveals that sumoylation promotes the ability of SnoN to associate with the histone acetylation modulators HDAC1 and p300 with functional implications for SnoN suppression of TGFβ-Smad-induced EMT in mammary epithelial and carcinoma organoids." (PMID 37414747, 2023). "Importantly, we further demonstrate that catalytic inactivation of HDAC1 or HDAC2 sensitizes cells to specific cancer drugs." (PMID 35994477, 2022). "Moreover, HDAC1 has been demonstrated to promote cancer progression by activating HIF1α/VEGFA, ROS/TNF-α, and c-Myc/miR-34a signaling pathways." (PMID 35053925, 2022). "Finally, H6M exerted robust HDAC1/cancer cell inhibitory activities compared with a known HDAC inhibitor SAHA." (PMID 35056740, 2022). "Recent studies suggest that HDAC1 has been identified as a therapeutic target for cancer treatment." (PMID 35053925, 2022). "Therefore, to address the clinical applicability of HDAC1 inhibitors for controlling NANOGhi-refractory cancer, we first measured the viability of CT26 P0, CT26 P3, or CT26 P3-siNANOG cells after in vitro treatment with FK228, MS-275, or MGCD0103." (PMID 35104240, 2022). "Further immunofluorescence results revealed that the coexpression of TOPK/NF-κB p65 and TOPK/p-IκBα increased in cSCC cancer tissues; then, HDAC1 and NF-κB p65 activation-related proteins decreased in cSCC cells with knocking down TOPK, while overexpression of TOPK showed opposite effects." (PMID 35756488, 2022).